MTHFD1 (methylenetetrahydrofolate dehydrogenase, cyclohydrolase and formyltetrahydrofolate synthetase 1)
Description:
Trifunctional enzyme that catalyzes the interconversion of three forms of one-carbon-substituted tetrahydrofolate: (6R)-5,10-methylene-5,6,7,8-tetrahydrofolate, 5,10-methenyltetrahydrofolate and (6S)-10-formyltetrahydrofolate. These derivatives of tetrahydrofolate are differentially required in nucleotide and amino acid biosynthesis, (6S)-10-formyltetrahydrofolate being required for purine biosynthesis while (6R)-5,10-methylene-5,6,7,8-tetrahydrofolate is used for serine and methionine biosynthesis for instance.
Synonyms: MTHFC; MTHFD; CIMAH
Tractability: Small molecule: a structure with a bound ligand is known; a high-quality ligand is known; it has a high-quality binding pocket. PROTAC: ubiquitination databases record sites on it; its protein half-life has been measured; a small molecule that binds it is known.
Target class: Enzyme
Chemical probes: TH9619 (high quality)
Safety:
Unwanted effects reported when the protein is acted on. In parentheses: how it was acted on, where the effect was seen, and who reports it.
drug toxicity (source: ClinPGx)
Gene: Protein-coding gene on chromosome 14 (64,388,031 to 64,463,457, forward strand). Ensembl gene ENSG00000100714.
Subcellular location: Cytoplasm
Subcellular location (Human Protein Atlas): Cytosol
Pathways (Reactome):
Metabolism: Metabolism of folate and pterines
Gene Ontology:
Molecular function: formate-tetrahydrofolate ligase activity; methenyltetrahydrofolate cyclohydrolase activity; methylenetetrahydrofolate dehydrogenase (NADP+) activity; protein binding; ATP binding; catalytic activity
Biological process: 10-formyltetrahydrofolate biosynthetic process; folic acid metabolic process; L-methionine biosynthetic process; purine nucleotide biosynthetic process; tetrahydrofolate interconversion; embryonic neurocranium morphogenesis; embryonic viscerocranium morphogenesis; heart development; neural tube closure; somite development; neutrophil homeostasis; transsulfuration
Cellular component: cytosol; extracellular exosome; membrane; mitochondrion; cytoplasm
Genetic constraint (gnomAD): Loss-of-function variants: 36 observed, 93.14 expected, observed/expected ratio (o/e) 0.39, 90% interval 0.29 to 0.51. The upper end of that interval is the gene's LOEUF score, 0.51, which puts it in group 2 of 6, group 1 being the genes least tolerant of losing a copy. Missense variants: 816 observed, 1,078.8 expected, observed/expected ratio (o/e) 0.76, 90% interval 0.71 to 0.8. Synonymous variants: 360 observed, 397.07 expected, observed/expected ratio (o/e) 0.91, 90% interval 0.83 to 0.99.
Gene-disease validity (ClinGen):
ClinGen rates the evidence that MTHFD1 causes each of these diseases.
combined immunodeficiency and megaloblastic anemia with or without hyperhomocysteinemia (autosomal recessive): Definitive.
Homologues: Orthologues: macaque MTHFD1 (98% identical), chimpanzee MTHFD1 (98% identical), dog MTHFD1 (95% identical), mouse Mthfd1 (93% identical), rabbit MTHFD1 (93% identical), pig MTHFD1 (93% identical), rat Mthfd1 (93% identical), guinea pig MTHFD1 (92% identical), tropical clawed frog mthfd1 (82% identical), zebrafish mthfd1b (77% identical), zebrafish mthfd1a (56% identical). Paralogues in human: MTHFD1L (61% identical), MTHFD2 (14% identical), MTHFD2L (13% identical).
Diseases named in the same sentence as MTHFD1 in open-access papers:
MTHFD1 is named in the same sentence as 82 diseases in open-access papers, as found by Europe PMC text mining. Sharing a sentence is not in itself a finding about the gene and the disease. The quoted sentences say what the papers report.
colorectal cancer (12 papers, 2013 to 2025). A primary or metastatic malignant neoplasm that affects the colon or rectum. "MTHFD1 is upregulated in multiple tumors such as cholangiocarcinoma, colorectal cancer, melanoma, and hematologic malignancies, which is related to tumor apoptosis, proliferation, migration and drug resistance." (PMID 38336749, 2024). "Our aim was to elucidate the function of MTHFD1 in colorectal cancer (CRC)." (PMID 39571599, 2024). "MTHFD1 maintains redox homeostasis in the folic acid metabolism process in metastatic colorectal cancer cells and serves as a potential therapeutic target for colorectal cancer." (PMID 38336749, 2024). "Indeed, both DHFR and MTHFD1 have been found to be overexpressed in colorectal cancer tumours compared to healthy tumour epithelia." (PMID 33498690, 2021). "Indeed, our results suggest that MTHFD1, 2 could be very interesting targets for the treatment of colorectal cancer." (PMID 38540202, 2024). "In colorectal cancer (CRC), MTHFD1 regulated autophagic processes to facilitate tumor growth and metastasis through the PI3K–AKT–mTOR signaling pathway." (PMID 39857769, 2025). "This suggests that BBR may also play a role by directly targeting MTHFD1 and MTHFD1L in colorectal cancer cells." (PMID 38049785, 2023). "In our previous systematic review and recent literature search for pharmacogenetic studies of colorectal cancer patients treated with fluoropyrimidines, no other studies were identified that included an analysis of DHFR, SHMT or MTHFD1 genotypes." (PMID 24167597, 2013).
lung carcinoma (7 papers, 2007 to 2024). "Together, these and the published data show that serine synthesis and catabolism enzymes are overexpressed in lung cancer, that their expression correlates with a metabolic stress marker and that MTHFD1/2 mRNA expression is linked to poor survival in adenocarcinoma." (PMID 38515202, 2024). "Regarding MTHFD1, besides its connection with survival outcomes in lung cancer patients with WT KRAS, its high expression was also associated to poorer survival in patients with KRAS/LKB1 co-mutations." (PMID 38997257, 2024). "In lung cancer, knockdown of MTHFD1 significantly increases the percentage of apoptotic tumor cells." (PMID 38336749, 2024). "Moreover, protein levels of RRM2 were slightly reduced in either MTHFD2 or SLC2A1 knockdown lung cancer cells, but no alteration of MTHFD1 and SLC2A1 in RRM2 knockdown cells." (PMID 33664854, 2021). "In lung cancer patients with KRAS WT, except for MTHFD1, the expression levels of G6PD, IDH1, and ME1 were not correlated with the patient survival time." (PMID 38997257, 2024).
folate deficiency (6 papers, 2017 to 2024). A nutritional condition produced by a deficiency of FOLIC ACID in the diet. "MTHFD1 plays a role in the development of neural tube defects—a congenital disorder due to folic acid deficiency in pregnant mothers." (PMID 34940850, 2022). "In particular, nuclear enrichment of folate cofactors and MTHFD1 can protect de novo thymidylate biosynthesis during folate deficiency." (PMID 34502300, 2021). "Altered activity of MTHFD1 may affect the ability to deal with folate deficiency and polymorphisms in MTHFD1 have been shown to lead to genome-wide decrease in DNA methylation." (PMID 39623445, 2024). "In folate deficiency, MTHFD1 is preferentially located in the nucleus." (PMID 35735795, 2022). "Folic acid deficiency, MTHFD1 rs2236225, MTHFR rs1801133, MTRR rs1801349 and RFC1 rs1051226 polymorphisms may be maternal risk factors of NTDs." (PMID 30867013, 2019). "We have shown that the common rs2236225 polymorphism in the MTHFD1 gene is an important modulator of CHD risk, especially under conditions of folate deficiency." (PMID 35735795, 2022). "The most sensitive pathways to folate deficiency are the MTCH and MTD activities of MTHFD1, MTHFR, MTR, DNMT, DHFR, and TYMS (row showing absolute flux differences between folate levels)." (PMID 28400561, 2017).
melanoma (6 papers, 2017 to 2024). A malignant, usually aggressive tumor composed of atypical, neoplastic melanocytes. "For instance, it has been postulated that MTHFD1 supports metastatic spread in melanoma by acting as a source of NADPH, which can contribute to glutathione recycling and antioxidant capacity." (PMID 33498690, 2021). "Two NADPH-generating enzymes, ALDH1L2 and MTHFD1, were identified as suppressors of ROS-mediated toxicity in metastasizing melanoma cells." (PMID 28181495, 2017). "Similarly, knocking down MTHFD1 can reduce the antioxidant stress ability of tumor cells, thus inhibiting the distant metastasis of melanoma." (PMID 38336749, 2024).
neural tube defect (6 papers, 2011 to 2022). A congenital defect characterized by failure of the neural tube to close completely; this results in the presence of openings in the brain or spinal cord. "The transition from G to A (rs2236225) in the MTHFD1 gene that results in an alteration of ARG-653-GLN is clinically associated with susceptibility to neural tube defects (NTDs) sensitive to folates." (PMID 21615938, 2011). "The common R653Q variant (MTHFD1 c.1958 G > A; rs2236225, ~20% QQ in European populations) compromises the synthetase activity of MTHFD1 and has been identified as a risk factor for neural tube defects (NTD), heart defects, intrauterine growth restriction, and pregnancy loss." (PMID 35011003, 2021). "Moreover, alterations in the MTHFD1 enzyme have been shown to increase serum Hcy concentrations and the risk of folate-sensitive neural tube defects (53, –55)." (PMID 26342040, 2015). "Previous studies have supported that MTHFD1 c.1958G>A (rs2236225) polymorphism is able to reduce the activity and stability of the MTHFD1 enzyme and has been associated with an increased risk of neural tube defects and unexplained second semester pregnancy loss." (PMID 25544792, 2014). "The methylenetetrahydrofolate dehydrogenase (MTHFD1) gene, as one of the key genes involved in the folate pathway, has been reported to play a critical role in the pathogenesis of neural tube defects (NTDs)." (PMID 24977710, 2014).
Immunodeficiency (5 papers, 2016 to 2024). Failure of the immune system to protect the body adequately from infection, due to the absence or insufficiency of some component process or substance. "MTHFD1 deficiency is a recently discovered metabolic disorder characterized by severe combined immunodeficiency, megaloblastic anemia, and neurological deficits." (PMID 29713328, 2018). "Additional genetic defects in MTHFD1, RMRP, CORO1A, PNP, DOCK8, ATM, and BCL11B, among others also cause combined immunodeficiencies, which can be detected by low TREC copy number analysis." (PMID 29713328, 2018). "In addition, genes related to immune diseases (e.g., BID, SMARCD3, ATP6V1E1, NFKB2), energy metabolism (e.g., HAO1, NDUFA7, CERS4, MTHFD1), and other factors were also screened." (PMID 38750582, 2024).
cholangiocarcinoma (3 papers, 2021 to 2024). A carcinoma that arises from the intrahepatic biliary tree (intrahepatic cholangiocarcinoma) or from the junction, or adjacent to the junction, of the right and left hepatic ducts (hilar cholangiocarcinoma). "In cholangiocarcinoma, MTHFD1 reduces the ROS content in tumor cells, and induces resistance to gemcitabine, thus enhancing the progressive phenotype of tumors." (PMID 38336749, 2024). "With further confirmation, the overall survival rate data from the TCGA database displayed a difference between cholangiocarcinoma patients with higher or lower expression of MTHFD1." (PMID 33934113, 2021). "MTHFD1 has been found to induce NADPH production and reduce the ROS content in cholangiocarcinoma cells." (PMID 38336749, 2024). "Taken together, we proved that MTHFD1 overexpression links the cellular redox status with enhanced gemcitabine chemoresistance in the HyPer-low subpopulation CCA cells and cholangiocarcinoma cells." (PMID 33934113, 2021). "Furthermore, the MTHFD1 inhibitor antifolate compound methotrexate (MTX) increased cellular ROS, and combining gemcitabine with MTX effectively suppressed cholangiocarcinoma cell growth." (PMID 33934113, 2021).
cleft lip (3 papers, 2014 to 2023). Congenital defect in the upper lip where the maxillary prominence fails to merge with the merged medial nasal prominences. "The MTHFD1 1958G>A polymorphism has significantly increased the risk of developing cleft lip and palate in cases that inherit one copy or two copies of this polymorphism." (PMID 25129243, 2014). "Several studies established associations between MTHFD1 and MTHFD2 gene variants and various health conditions such as cancer, cleft lip and palate, Down’s syndrome, and miscarriage." (PMID 37630697, 2023). "The terms for searching were “cleft lip OR cleft palate OR CLP OR CL/P OR oral facial cleft OR OFC” AND “methylenetetrahydrofolate dehydrogenase (NADP+ dependent) 1 OR methenyltetrahydrofolate cyclohydrolase formyltetrahydrofolate synthetase OR MTHFD1 OR MTHFD”." (PMID 26834978, 2015).
colon cancer (3 papers, 2013 to 2021). "Even more intriguing was the significantly reduced MTHFD1 1958AA frequency in colon cancer patients as compared to controls and its association with a 75% reduction of colon cancer risk." (PMID 28968444, 2017). "For G401A, MTHFD1 G401A polymorphism was associated with a decreased colon cancer risk under dominant model." (PMID 23894459, 2013). "For G401A, the data showed that MTHFD1 G401A polymorphism was associated with a decreased colon cancer risk under dominant model (OR = 0.89, 95% CI = 0.80–0.99, P = 0.04)." (PMID 23894459, 2013). "Therefore our study demonstrates that the MTHFD1 1958AA is associated to a reduction for cancer risk, in particular for colon cancer." (PMID 28968444, 2017). "We demonstrated that the combined inhibition of xCT and MTHFD1 is synergetic and is specific for metastatic colon cancer cell lines." (PMID 33498690, 2021). "Meanwhile, the MTHFD1 G401A might play a protective role in the development of colon cancer." (PMID 23894459, 2013).
congenital heart disease (3 papers, 2022 to 2024). A heart disease that is present at birth. "MTHFD1 gene may affect the embryonic development by elevated homocysteine levels, DNA synthesis and DNA methylation, but limited number of genetic variants of MTHFD1 gene was focused on the association with congenital heart disease (CHD)." (PMID 35100977, 2022). "Given the disparity in baseline characteristics between the case and control groups, adjustments were made to investigate the impact of maternal FAS, progeny MTHFD1, and MTHFD2 gene polymorphisms, along with their interactions, on congenital heart disease." (PMID 37630697, 2023). "Variants in the MTHFD1 and MTHFD2 genes associated with congenital heart disease in humans." (PMID 39062651, 2024).
gastric cancer (3 papers, 2007 to 2024). A primary or metastatic malignant neoplasm involving the stomach. "We found that overexpression of MTHFD2, but not MTHFD1, is associated with reduced overall and disease-free survival in gastric cancer." (PMID 38723197, 2024).
hepatocellular carcinoma (3 papers, 2021 to 2025). A malignant tumor that arises from hepatocytes. "Research suggests that the overexpression of MTHFD1 in hepatocellular carcinoma was associated with poorer survival and recurrence." (PMID 39857769, 2025). "MTHFD1 expression was associated with a worse prognosis in acute leukemia and hepatocellular cancer patients." (PMID 35693982, 2022). "MTHFD1 was overexpressed in hepatocellular carcinoma and associated with a poor prognosis." (PMID 35693982, 2022). "MTHFD1, methylenetetrahydrofolate dehydrogenase, cyclohydrolase, and formyltetrahydrofolate synthetase 1, has also been reported to be overexpressed in hepatocellular carcinoma and to predict poor survival and recurrence." (PMID 33718182, 2021).
liver cancer (3 papers, 2016 to 2023). An epithelial or non-epithelial malignant neoplasm that arises from the liver. "MTHFD1 was found to be associated with a protective role for colon and liver cancer risks prevalent in men22 and is consistent with the present study that MTHFD1 is significantly and positively associated with longevity in men (P = 1.09 × 10−7) but not significant in women (P = .95)." (PMID 30294719, 2018). "Studies have found that MTHFD1 deficiency can significantly inhibit the antioxidant defense ability of cells and inhibit the distant metastasis of tumors, which indicates that the high expression of MTHFD1 in liver cancer tissues indicates a poor prognosis." (PMID 36968582, 2023). "Forty-seven primary liver cancer patients were genotyped for ten polymorphisms: DHFR 19bp ins/del, TS 2rpt-3rpt, MTHFD1 1958G>A, MTHFR 677C>T, MTR 2756A>G, MTRR 66A>G, RFC1 80G>A, SHMT1 1420C>T, BHMT 716 A>G, TC II 776C>G." (PMID 27936032, 2016).
abruptio placentae (2 papers, 2014 to 2024). "It is noteworthy that women who harbor the AA homozygote for the MTHFD1 G1958A polymorphism are almost three times more likely to develop severe abruptio placentae during their pregnancy than women who are ‘GA’ or ‘GG’." (PMID 24977710, 2014). "MTHFD1 gene polymorphism is mainly associated with placental influence on recurrent pregnancy loss, congenital heart diseases in early infants, intrauterine growth restriction, preeclampsia, placental abruption, and fetal death." (PMID 38435941, 2024).
acute leukemia (2 papers, 2022). A clonal (malignant) hematopoietic disorder with an acute onset, affecting the bone marrow and the peripheral blood. "Similarly, the deregulation of folate cycle enzymes, such as the high expression of the MTHFD1 gene, affects survival rates in acute leukemia patients." (PMID 35323710, 2022).
acute lymphoblastic leukaemia (2 papers, 2023). "In mammals, abnormality in the folate cycle accompanies various diseases, including tumours, and mutations in its human homologue MTHFD1 are associated with congenital heart defects and childhood acute lymphoblastic leukaemia." (PMID 37859837, 2023).
anemia (2 papers, 2025). A reduction in the number of red blood cells, the amount of hemoglobin, and/or the volume of packed red blood cells. "Higher ALB level, female, ABCB1 rs1045642, MTHFR rs1801131, and MTHFD1 rs2236225 were associated with lower risk of anemia, while the combination of furosemide, torasemide, bumetanide, and levetiracetam associating with higher risk." (PMID 40832604, 2025). "In our study, AA mutant homozygote on MTHFD1 rs2236225 was associated with a lower risk of anemia, while the wild-type homozygote GG associated with a lower risk of leukopenia." (PMID 40832604, 2025). "A study published in 2011 reported a significant association between an increased likelihood of hematologic toxicity (anemia) and the MTHFD1 rs2236225 AA/AG genotypes in 50 children from multiethnic ancestry (Caucasian, Afro-Caribbean, Indian) with OS, treated with MTX (p = 0.044)." (PMID 40430876, 2025).
anterior encephalocele (2 papers, 2023 to 2024). "The SNPs between MTHFR and MTHFD1 are associated with anterior encephalocele, a rare congenital anomaly of the central nervous system related to genetic defects in folate metabolism." (PMID 36980585, 2023). "MTHFD1 rs2236225 (1958 G > A) and MTHFR rs1801131 (1,298 A > C) are in relation to anterior encephalocele susceptibility in Northeast India." (PMID 38650623, 2024).
aortic stenosis (2 papers, 2021 to 2023). Aortic valve stenosis is a aortic valve disease caused by the incomplete opening of the aortic valve. "Population investigations further indicated that the Arg653Gln variant in MTHFD1 gene increased the risk of valvular defect aortic stenosis and conotruncal defects." (PMID 37630697, 2023). "With respect to the subtypes of CHD, positive associations of MTHFD1 rs2236225 with atrial septal defects, tetralogy of Fallot, and aortic stenosis were observed." (PMID 35186819, 2021).
breast carcinoma (2 papers, 2022 to 2024). "Analogous results were obtained with the CDK12 inhibitor, THZ531 which, in line with the effects observed in CDK12-OE MCF10A cells, inhibited PSAT1 and MTHFD1 expression in CDK12HIGH breast cancer cells both at the mRNA and protein level." (PMID 35550508, 2022).